NFKB1 (nuclear factor kappa B subunit 1)
Description:
NF-kappa-B is a pleiotropic transcription factor present in almost all cell types and is the endpoint of a series of signal transduction events that are initiated by a vast array of stimuli related to many biological processes such as inflammation, immunity, differentiation, cell growth, tumorigenesis and apoptosis. NF-kappa-B is a homo- or heterodimeric complex formed by the Rel-like domain-containing proteins RELA/p65, RELB, NFKB1/p105, NFKB1/p50, REL and NFKB2/p52 and the heterodimeric p65-p50 complex appears to be most abundant one. The dimers bind at kappa-B sites in the DNA of their target genes and the individual dimers have distinct preferences for different kappa-B sites that they can bind with distinguishable affinity and specificity. Different dimer combinations act as transcriptional activators or repressors, respectively. NF-kappa-B is controlled by various mechanisms of post-translational modification and subcellular compartmentalization as well as by interactions with other cofactors or corepressors. NF-kappa-B complexes are held in the cytoplasm in an inactive state complexed with members of the NF-kappa-B inhibitor (I-kappa-B) family. In a conventional activation pathway, I-kappa-B is phosphorylated by I-kappa-B kinases (IKKs) in response to different activators, subsequently degraded thus liberating the active NF-kappa-B complex which translocates to the nucleus. NF-kappa-B heterodimeric p65-p50 and RelB-p50 complexes are transcriptional activators. The NF-kappa-B p50-p50 homodimer is a transcriptional repressor, but can act as a transcriptional activator when associated with BCL3. NFKB1 appears to have dual functions such as cytoplasmic retention of attached NF-kappa-B proteins by p105 and generation of p50 by a cotranslational processing. The proteasome-mediated process ensures the production of both p50 and p105 and preserves their independent function, although processing of NFKB1/p105 also appears to occur post-translationally. p50 binds to the kappa-B consensus sequence 5'-GGRNNYYCC-3', located in the enhancer region of genes involved in immune response and acute phase reactions. In a complex with MAP3K8, NFKB1/p105 represses MAP3K8-induced MAPK signaling; active MAP3K8 is released by proteasome-dependent degradation of NFKB1/p105. [Nuclear factor NF-kappa-B p105 subunit]: P105 is the precursor of the active p50 subunit (Nuclear factor NF-kappa-B p50 subunit) of the nuclear factor NF-kappa-B. Acts as a cytoplasmic retention of attached NF-kappa-B proteins by p105. [Nuclear factor NF-kappa-B p50 subunit]: Constitutes the active form, which associates with RELA/p65 to form the NF-kappa-B p65-p50 complex to form a transcription factor. Together with RELA/p65, binds to the kappa-B consensus sequence 5'-GGRNNYYCC-3', located in the enhancer region of genes involved in immune response and acute phase reactions.
Synonyms: KBF1; p105; NFKB-p50; p50; NF-kappaB; NFkappaB; NF-kB1; CVID12; EBP-1; NF-kB; NF-kappa-B1; NF-kappabeta; NFKB-p105
Tractability: Small molecule: a drug acting on it is in phase 2 or 3 trials; a structure with a bound ligand is known; a high-quality ligand is known; it belongs to a druggable protein family. Antibody: its Gene Ontology location is reachable by antibodies, with high confidence. PROTAC: UniProt records ubiquitination sites on it; ubiquitination databases record sites on it; its protein half-life has been measured; a small molecule that binds it is known.
Target class: Other cytosolic protein
Gene: Protein-coding gene on chromosome 4 (102,500,937 to 102,617,302, forward strand). Ensembl gene ENSG00000109320.
Subcellular location: Cytoplasm (Nuclear factor NF-kappa-B p105 subunit); Nucleus (Nuclear factor NF-kappa-B p50 subunit); Cytoplasm
Subcellular location (Human Protein Atlas): Nucleoplasm; Cytosol
Pathways (Reactome):
Immune System: Activation of NF-kappaB in B cells; CD209 (DC-SIGN) signaling; CLEC7A (Dectin-1) signaling; CLEC7A/inflammasome pathway; DEx/H-box helicases activate type I IFN and inflammatory cytokines production; Downstream TCR signaling; FCERI mediated NF-kB activation; Interleukin-1 processing; Interleukin-1 signaling; MAP3K8 (TPL2)-dependent MAPK1/3 activation; Neutrophil degranulation; RIP-mediated NFkB activation via ZBP1; Regulation of PD-L1(CD274) transcription; TAK1-dependent IKK and NF-kappa-B activation; TRAF6 mediated NF-kB activation; The NLRP3 inflammasome
Disease: HCMV Early Events; IkBA variant leads to EDA-ID; Purinergic signaling in leishmaniasis infection; SARS-CoV-1 activates/modulates innate immune responses
Cellular responses to stimuli: Regulation of NFE2L2 gene expression; Senescence-Associated Secretory Phenotype (SASP); Turbulent (oscillatory, disturbed) flow shear stress activates signaling by PIEZO1 and integrins in endothelial cells
Signal Transduction: NF-kB is activated and signals survival; Regulated proteolysis of p75NTR
Cell-Cell communication: Activation of STAT3 by cadherin engagement
Chromatin organization: PKMTs methylate histone lysines
Developmental Biology: Transcriptional regulation of white adipocyte differentiation
Gene expression (Transcription): Transcriptional Regulation by VENTX
Gene Ontology:
Molecular function: actinin binding; DNA-binding transcription activator activity, RNA polymerase II-specific; DNA-binding transcription factor activity; DNA-binding transcription factor activity, RNA polymerase II-specific; DNA-binding transcription repressor activity, RNA polymerase II-specific; identical protein binding; protein binding; RNA polymerase II cis-regulatory region sequence-specific DNA binding; RNA polymerase II transcription regulatory region sequence-specific DNA binding; transcription cis-regulatory region binding; protein sequestering activity; chromatin binding; cis-regulatory region sequence-specific DNA binding; DNA binding; sequence-specific DNA binding; transcription coregulator activity
Biological process: antibacterial innate immune response; canonical NF-kappaB signal transduction; cellular response to angiotensin; cellular response to interleukin-6; cellular response to lipopolysaccharide; cellular response to mechanical stimulus; cellular response to nicotine; negative regulation of cytokine production involved in inflammatory response; negative regulation of gene expression; negative regulation of inflammatory response; negative regulation of transcription by RNA polymerase II; negative regulation of vitamin D biosynthetic process; non-canonical NF-kappaB signal transduction; positive regulation of canonical Wnt signaling pathway; positive regulation of cholesterol efflux; positive regulation of DNA-templated transcription; positive regulation of hyaluronan biosynthetic process; positive regulation of lipid storage; positive regulation of macrophage derived foam cell differentiation; positive regulation of miRNA metabolic process; positive regulation of transcription by RNA polymerase II; regulation of transcription by RNA polymerase II; tumor necrosis factor-mediated signaling pathway; inflammatory response; negative regulation of apoptotic process; and 14 more
Cellular component: chromatin; cytoplasm; cytosol; I-kappaB/NF-kappaB complex; nucleoplasm; nucleus; extracellular region; NF-kappaB p50/p65 complex; secretory granule lumen; specific granule lumen
Genetic constraint (gnomAD): Loss-of-function variants: 8 observed, 80.92 expected, observed/expected ratio (o/e) 0.0989, 90% interval 0.057 to 0.18. The upper end of that interval is the gene's LOEUF score, 0.18, which puts it in group 1 of 6, group 1 being the genes least tolerant of losing a copy. Missense variants: 670 observed, 1,017.2 expected, observed/expected ratio (o/e) 0.66, 90% interval 0.62 to 0.7. Synonymous variants: 369 observed, 386.16 expected, observed/expected ratio (o/e) 0.96, 90% interval 0.88 to 1.04.
Gene-disease validity (ClinGen):
ClinGen rates the evidence that NFKB1 causes each of these diseases.
immunodeficiency, common variable, 12 (autosomal dominant): Moderate.
Homologues: Orthologues: chimpanzee NFKB1 (100% identical), macaque NFKB1 (99% identical), dog NFKB1 (92% identical), rabbit NFKB1 (90% identical), mouse Nfkb1 (87% identical), rat Nfkb1 (87% identical), guinea pig NFKB1 (86% identical), pig NFKB1 (86% identical), tropical clawed frog nfkb1 (64% identical), zebrafish nfkb1 (32% identical), Drosophila melanogaster dl (22% identical), Drosophila melanogaster Dif (19% identical). Paralogues in human: NFKB2 (40% identical), REL (18% identical), RELB (16% identical), RELA (16% identical).
Diseases named in the same sentence as NFKB1 in open-access papers:
NFKB1 is named in the same sentence as 1,568 diseases in open-access papers, as found by Europe PMC text mining. Sharing a sentence is not in itself a finding about the gene and the disease. The quoted sentences say what the papers report.
breast carcinoma (2,609 papers, 2003 to 2026). "The gene NFKB1 was found to be mutated and elevated in breast cancer, while REL is suggested to play some role as the NFKB genes belong to the REL family." (PMID 28607444, 2017). "NFKB1 heterozygous and variant genotypes were associated with breast cancer risk in invasive ductal carcinoma (IDC) and ductal carcinoma in situ (DCIS), but not in invasive lobular carcinoma (ILC)." (PMID 25559835, 2014). "For pre-menopausal women, significant associations with breast cancer risk were observed for NFKB1 ins/del and del/del genotypes, NFKBIA CT genotype, IL-8 TT genotype, IL-10 TT genotype, and TNF c.-418 GA and AA genotypes." (PMID 25559835, 2014). "For post-menopausal women, significant associations with breast cancer risk were observed for NFKB1 ins/del and del/del genotypes, IL-8 TT genotype, IL-10 TT genotype, TNF c.-418 GA and AA genotypes, and TNF c.-488 GA genotype." (PMID 25559835, 2014). "NFKB1 c.-798_-795delATTG ins/del and del/del genotypes, and IL-10 c.-854 TT genotype were associated with increased breast cancer risk, while IL8 c.-352 TT genotype, TNF c.-418 GA and AA genotypes, and c.-488 GA genotype were significantly associated with a reduced risk." (PMID 25559835, 2014). "We analyzed not only the association of individual polymorphisms and breast cancer risk, but also the effects of combinations of functionally related polymorphisms (NFKB1 and NFKBIA; IL-8 and IL-10; and TNF c.-418 and c.-488), menopausal status, histopathological type, and cancer grading." (PMID 25559835, 2014). "Although one of the real microgravity studies with human breast cancer cell lines indicated an upregulation of NFKB1, NFKB3, NFKBIA, and NFKBIB but a reduced protein content." (PMID 40577073, 2025). "Studies have shown that NFKB1 has a role in tumor progression, metastasis, and resistance to chemotherapy in breast cancer patients." (PMID 37686072, 2023). "Mutations in promoter sequences that affect NFKB1 expression or NF-κB-dependent expression of target genes have been described in oral, bladder, and breast cancer." (PMID 34440093, 2021). "The radiogene NFKB1, which transactivates several pro-inflammatory genes, was found to be overexpressed in radioresistant breast cancer cells and tissue." (PMID 33898418, 2021). "Analysis with ONCOMINE demonstrated that the mRNA expression levels of MMP9 and NFKB1 were significantly higher in metastatic breast cancer cells than in normal tissues." (PMID 34335799, 2021). "In primary breast cancer tissues, the mean methylation level was 1.40 ± 0.90% for the NFKB1 gene and 1.49 ± 0.50% for the RELA gene, while that of two genes in normal mammary tissues was 1.51 ± 0.66% and 1.60 ± 0.19%, respectively." (PMID 31382678, 2019). "This evidenced that PAR1 activity contributed to LEC migration and CCID formation, which was stimulated by RELA/NFKB1 - MMP1 signals generated in MDA-MB231 breast cancer spheroids." (PMID 26513020, 2015). "This was the likely reason why the activities of both pathways did not stimulate CCID formation beyond the activity of just RELA/NFKB1 in MDA-MB231 breast cancer cells and also in LECs." (PMID 26513020, 2015). "NFκB exists as a heterodimer composed of RelA (p65) and NFκB1 (p50) subunits in most cells, where it regulates the expression of multiple genes and contributes to the pathogenesis of various diseases, including breast cancer." (PMID 26696754, 2015). "RELA, RELB, CREL, NFKB1 and NFKB2, and the upstream regulators NEMO and NIK were knocked-down in lymph endothelial cells (LECs) and in MDA-MB231 breast cancer spheroids to study the contribution of NF-κB in vascular barrier breaching." (PMID 26513020, 2015). "Increased expression of MTA2 leads to estrogen independent growth of human mammary carcinoma cells and increased expression of NFKB1 expression increases the invasive potential of carcinoma cells." (PMID 22060274, 2011).
breast carcinoma (continued). "NFκB1 activity has been observed in various types of cancer, including breast cancer and CRC, to contribute to tumor angiogenesis and progression." (PMID 21738780, 2011). "Early-stage primary breast cancer selected for lower ER content showed two- to fourfold increased NFkB1 and RelA DNA binding over a second set of primary breast cancer with higher ER content." (PMID 17700572, 2007). "Indeed, we find that vehicle-treated ErbB2-induced breast cancer tissue expresses Il1a, Il1b, Il6, and Nfkb1 at a measurable level." (PMID 37098526, 2023). "Furthermore, RELA, a subunit of the NFKB1, has also been identified as a target for preventing NFKB1-driven tumors, as this subunit is more highly expressed in breast cancer compared to adjacent tissues." (PMID 37686072, 2023). "We propose that relatively low levels of miR-214 in mammosphere-derived epithelial cells from mammals with low mammary cancer incidence, allow for constitutive gene nuclear factor kappa B subunit 1 expression and apoptosis in response to 7, 12-Dimethylbenz(a)anthracene." (PMID 37789172, 2023). "Upregulation of NFKB1 can promote the invasiveness of breast cancer cells in vitro." (PMID 36601599, 2022). "We further verified the effects of hypoxia enhancing miRNA-induced oxidative stress, cell migration, induction of EMT, expression of hypoxia-linked genes such as VHL, HIF-1α, and NFκB1, and expression of inflammation-associated genes such as VEGFA, COX-2, and EP4 in breast cancer cell lines." (PMID 32707933, 2020). "We have previously shown that miR655 overexpression in MCF7 cells promotes COX-2 expression and proposed that this could be via NFκB1 upregulation in the ER-positive breast cancer cell line." (PMID 32707933, 2020). "Moreover, enhanced level of Nfatc2 and Nfkb1 positively correlated with Ets1 expression in the human breast cancer specimens." (PMID 30467308, 2018). "We found that particularly in breast cancer cells, CD47 expression is increased by an inflammatory pathway whereby the NFKB1 transcription factor directly regulates the expression of the gene by binding to a specific constituent enhancer within an active breast cancer SE (proposed mechanism)." (PMID 28378740, 2017). "NFKB1, NFKBIA, IL-8, IL-10, and TNF polymorphisms could serve as useful predictive biomarkers for breast cancer risk among women in East China." (PMID 25559835, 2014). "Moreover, NFKB1/RELA induces breast cancer progression by upregulating ETS1." (PMID 34335799, 2021). "The rs4648090 polymorphism has also been related to decreased risk of breast cancer among women with European ancestry and to interact with other SNPs in the IFNG, IRF2, IL6, and NFKB1 genes to affect risk of colon cancer, and with IRF6 and NFKB1 genes for risk of rectal cancer." (PMID 30781516, 2019). "Also, knock-down of NFKB1 in the inflammatory breast cancer cell line (SUM-149) suggests that NFKB1 expression positively regulates Rho C expression and cell motility, which may contribute to the metastatic phenotype of inflammatory breast cancer." (PMID 30205516, 2018). "These signaling pathways and targets are likely key mechanisms through which BO treats breast cancer, including pathways, such as those of STAT3, NFKB1, PI3K-Akt, PD-L1 expression, and the PD-1 checkpoint." (PMID 40076902, 2025). "CUR hindered the breast cancer cell inflammatory cytokines C-X-C Motif Chemokine Ligand (CXCL) 1 and −2 by regulating nuclear factor kappa B subunit 1 (NF-κB)." (PMID 40380246, 2025).